RPLP1P5 (ribosomal protein lateral stalk subunit P1 pseudogene 5)
Gene: Processed pseudogene on chromosome 2 (15,869,939 to 15,870,243, forward strand). Ensembl gene ENSG00000214657.
Diseases named in the same sentence as RPLP1P5 in open-access papers:
RPLP1P5 is named in the same sentence as 1 disease in open-access papers, as found by Europe PMC text mining. Sharing a sentence is not in itself a finding about the gene and the disease.
RPLP1P5 shares sentences with these, for which no sentence is quoted: ovarian carcinoma (1 paper).